TK1 (thymidine kinase 1)
Diseases named in the same sentence as TK1 in open-access papers (continued):
Sharing a sentence is not in itself a finding about the gene and the disease.
cancer (continued). "TK1 has been previously documented to enhance cancer progression, and high TK1 levels are predictive of poor prognosis in individuals with cancer." (PMID 36035114, 2022). "As TK1 is the predominant thymidine kinase present in normal proliferating cells as well as cancer cells, the role of mitochondrial cell-cycle independent TK2 in cancer must be further investigated." (PMID 35203388, 2022). "To investigate the potential role of TK1 in tumorigenesis, we performed a pan-cancer analysis of TK1 in TCGA database, which included 10,953 participants with 10,967 malignancies using cbioportal." (PMID 35311151, 2022). "More importantly, the majority of malignancies (25 of 33 types of cancer, 75.8%) presented with upregulated TK1 levels." (PMID 35311151, 2022). "This regulation of RNR was exploited as a strategy in cancer therapy through the treatment with dT as a single dCTP-depleting agent via dTTP synthesis by TK1." (PMID 35203388, 2022). "Numerous studies have further demonstrated that elevated TK1 levels have occur in the serum of many different types of cancers, including some of the most common cancers of the lung cancer, colon cancer, and breast cancer." (PMID 36035114, 2022). "Recently, it was shown that despite being a biomarker, TK1 also participates in cancer invasion and progression." (PMID 36035114, 2022). "Thymidine Kinase 1 (TK1) is primarily known as a cancer biomarker with good prognostic capabilities for both hematological and solid malignancies." (PMID 35239730, 2022). "With the recent discovery that TK1 localizes to the plasma membrane of malignant cells only, TK1 is now also considered a potential anti-cancer target suitable for immunotargeting." (PMID 35203388, 2022). "Recent research suggests that over-expressed TK1 promotes cancer cell invasion, proliferation, and progression." (PMID 36358602, 2022). "The [18F]-FLT compound enters cancer cells through specific nucleoside transporters and, once inside the cell, is being phosphorylated by thymidine kinase-1 and ultimately confined within the cell." (PMID 35563414, 2022). "Considering that the TK1 is important kinase in angiogenesis, the miR-320b suppressed cancer development by inhibiting IGF2BP2/TK1 manner." (PMID 35937999, 2022). "During the last 3 decades scientific evidence has shown that TK1 levels in the serum of cancer patients can be used as a biomarker for early cancer detection." (PMID 35239730, 2022). "The molecular mechanisms of cancer progression and metastasization involving TK1 have only been recently demonstrated." (PMID 34830698, 2021). "Serum TK1 has been used as a biomarker in health screening, cancer diagnosis and prognosis in human medicine." (PMID 34579716, 2021). "In human medicine, serum TK1 has been used in health screening and for cancer diagnosis and prognosis." (PMID 34579716, 2021). "Serum TK1 activity has been used as a biomarker for health screening to detect premalignant diseases and for cancer diagnosis and prognosis in human medicine." (PMID 34906077, 2021). "In cancer cells, the cell cycle-regulated expression of TK1 is disrupted, resulting in overexpression and leakage of TK1 into the blood." (PMID 34906077, 2021). "A paired comparison in 50 HCC patients showed that TK1 mRNA expression in cancer tissue was significantly higher than in adjacent normal tissue." (PMID 35127491, 2021). "Thymidine kinase 1 (TK1) participates in cell proliferation through the DNA salvage pathway and up-regulation of TK1 is an early sign of cancer development." (PMID 35127491, 2021). "Binding of the antibodies to TK1 was confirmed by Western blot in purified recombinant protein, cancer serum, and cell lysate." (PMID 32317865, 2020). "Second, previous studies examined the TK1 expression in the cancer tissues and we detected the TK1 levels in the serum." (PMID 32202305, 2020).
cancer (continued). "Thymidine kinase 1 (TK1) is a pyrimidine salvage pathway enzyme that is up-regulated in malignant tissues and elevated in the serum of cancer patients." (PMID 32317865, 2020). "Fully elucidating the mechanisms behind TK1 elevation in cancer cells and its correlation to cancer progression begins with understanding the regulatory mechanisms of TK1 expression." (PMID 33292474, 2020). "As early as the 1960s, fetal TK (TK1) activity was shown to be elevated in tumors and TK1 is abnormally high in the sera of several different cancer types including lung, colon, breast, and prostate." (PMID 33292474, 2020). "Although TK1 was initially proposed as a cancer biomarker for several blood cancers, it has also been shown to be a reliable biomarker for a wide variety of solid malignancies." (PMID 32317865, 2020). "Proliferation markers, such as proliferating cell nuclear antigen (PCNA), Ki-67, and thymidine kinase 1 (TK1), have potential as diagnostic tools and as prognostic factors in assessing cancer treatment and disease progression." (PMID 33292474, 2020). "Continued research is needed to identify specific networks affected by TK1 in order to elucidate its mechanistic role in cancer pathogenesis." (PMID 33292474, 2020). "Since then, various studies have shown that increased levels of TK1 are found in the sera of many different cancer types including some of the most commonly diagnosed: lung, colon, breast, and prostate." (PMID 33292474, 2020). "Thymidine kinase 1 (TK1) is involved in DNA synthesis and its activity correlates to outcome in cancer patients." (PMID 32161278, 2020). "Due to their high specificity monoclonal antibodies are ideal candidates for the specific targeting of TK1 in cancer cells." (PMID 32317865, 2020). "Surface expression of TK1 on the membrane of various cancer cell lines was analyzed with flow cytometry." (PMID 32317865, 2020). "Further comparisons between TK1 levels among all positive samples showed that levels of TK1 progressively increased with cancer stage, indicating a positive correlation between TK1 and cancer stage." (PMID 33292474, 2020). "p = 0.0001), breast (~ 70%, p = 0.0461) and colon (~ 50% p = 0.0216) cancer cells by effector cells was observed when anti-TK1 antibodies were added during ADCC experiments." (PMID 32317865, 2020). "Multiple studies have shown that TK1 levels in serum (sTK1) and tissues correlate with cancer progression, patient outcome and recurrence events." (PMID 32317865, 2020). "Antibodies 8G2, 3B4, 7HD and 5F7G11 detected TK1 on the membrane of various cancer cell lines, including lung, prostate, colon and breast." (PMID 32317865, 2020). "As a result of these findings and others, TK1 is not only a potentially viable biomarker for cancer recurrence, treatment monitoring, and survival, but is potentially more advantageous than current biomarkers." (PMID 33292474, 2020). "As a result of such findings, serum TK1 levels have obvious potential as a biomarker for cancer disease management." (PMID 33292474, 2020). "Several reviews of TK1 elaborate on various assays that have been developed to measure levels in the serum of cancer patients in clinical settings." (PMID 33292474, 2020). "Two of the custom antibodies, 3B4 and 5F7G11 showed consistent binding to MDA-MB-231 (breast) and PC3 (prostate) cancer cell lines, although antibody 5F7G11 showed low affinity for TK1 in indirect ELISA." (PMID 32317865, 2020). "Serum thymidine kinase 1 (sTK1) activity has been shown to correlate with the proliferative activity of cancer cells providing information regarding prognosis and treatment effectiveness in human patients with hematologic malignancies." (PMID 32133044, 2020). "Thymidine Kinase 1 (TK1) is a cell cycle regulated DNA synthesis enzyme that is up-regulated in malignant tissues during early stages of cancer development." (PMID 32317865, 2020).
cancer (continued). "For simple (n = 30), infiltrating duct (n = 41), and medullary (n = 12) carcinoma tissue samples, 83%, 63%, and 66% respectively stained positive for TK1." (PMID 33292474, 2020). "All samples for infiltrating lobular carcinoma (n = 3) and scirrhous carcinoma tissue (n = 11) stained positive for TK1." (PMID 33292474, 2020). "Future studies should determine the expression levels of TK1 in clinical specimens of various types of cancer." (PMID 31138881, 2019). "TK1 is an emerging biomarker in cancer diagnosis; however, its effectiveness in diagnosis and management for malignant pleural effusion (MPE) is unclear." (PMID 30985967, 2019). "TK1 is overexpressed in a number of different cancers, and several studies have used expression of this protein as a biomarker for cancer detection." (PMID 31589613, 2019). "Together, these data suggest that FTD would more effectively treat cancers with high TK1 expression than those with low TK1 expression." (PMID 31138881, 2019). "We therefore performed experiments to determine if the TK1 mechanism of action in cancer is distinct from its previously reported role in DNA damage, DNA replication, and DNA repair." (PMID 31589613, 2019). "In this study, for the first time, we generated TK1-specific-knock-out human cancer cell lines using the CRISPR/Cas9 genome editing system and then obtained cell lines with inducible TK1 expression." (PMID 31138881, 2019). "In this study, it was the first time to show that TK1 knockdown suppressed in vitro and in vivo carcinoma cell progression." (PMID 32064235, 2019). "The mRNA expression of TK1 in carcinoma cells as well as in normal thyroid follicular epithelial cells was investigated." (PMID 32064235, 2019). "Patient data from TCGA revealed that the TK1 gene expression is upregulated in cancer patients compared to normal healthy patients." (PMID 30214377, 2018). "We stained lung, breast, and colon tissue arrays containing healthy normal, healthy normal adjacent, cancer adjacent, and malignant tissue with anti-TK1 antibodies to establish overall expression of TK1." (PMID 30214377, 2018). "We also show that TK1 is upregulated in a significant population of cancer patient tissues and that TK1 gene expression is also upregulated in cancer patients compared to normal healthy patients." (PMID 30214377, 2018). "Serum TK1 (sTK1) has been used in many applications for the early detection and diagnosis of cancer, as it is found upregulated in cancer patients." (PMID 30214377, 2018). "We have seen similar results in the expression of TK1 in hematological malignancies vs. normal proliferating lymphocytes, where TK1 only localized to the membrane of the cancer cells." (PMID 30214377, 2018). "TK1 catalyzes the conversion of thymidine to deoxythymidine monophosphate (dTMP) is function as a proliferation marker in multiple cancer types." (PMID 29100421, 2017). "Western blots showed a general elevation in the levels of cellular RRM1, RRM2, and TK1 in cancer cell lines compared to normal cells." (PMID 28289079, 2017). "Increased TK1 activity can enhance the excision of genotoxic damage and thus promote resistance to many cancer therapies." (PMID 29018771, 2017). "Thymidine kinase (TK1) is an enzyme involved in DNA synthesis that leaks into the blood as a result of high cell turnover, particularly in the case of cancer." (PMID 27079872, 2016). "Low levels of TK1 are generally expressed in normal adult cells while high levels of TK1 are characteristic of cancer cells." (PMID 25881156, 2015). "From the viewpoint of FTD resistance, the downregulation of nucleoside transporters and TK1 involved in the dThd salvage pathway results in ineffective therapy against cancer cells." (PMID 25901475, 2015). "The aim of our work was to translate the results from previous studies into a sensitive and reproducible TK1 protein assay format for detection and quantification of TK1 in sera from dogs with malignancies." (PMID 26366881, 2015).
cancer (continued). "Serum TK1 determinations have been used clinically for many years as they provide valuable information to guide anti-cancer therapy both in human and in veterinary medicine." (PMID 25293656, 2014). "TK1 can be isolated from many different cell and tissue types, and elevated serum TK1 activity is documented in many types of cancer, nonetheless, the mechanism of TK entering the systemic circulation is not well understood." (PMID 24621590, 2014). "Thymidine kinase 1 (TK1) is a proliferation biomarker that has been found useful for prognostication in cancer patients." (PMID 23693054, 2013). "TK1 upregulation as an early event of cancer is a novel concept that has been addressed by only a few recent studies." (PMID 22778736, 2012). "As a biomarker, higher serum TK1 activity levels correlate with a more advanced cancer stage and grade." (PMID 22778736, 2012). "Thymidine kinase 1 (TK1) has been studied extensively, primarily as a diagnostic biomarker for a variety of cancer types." (PMID 22778736, 2012). "This prognostic potential includes the novel concept that upregulation of serum TK1 levels is an early event in cancer development." (PMID 22778736, 2012). "The concentration and activity of TK1 in blood serum of cancer patients are elevated, while TK1 in serum of healthy people is low or undetectable." (PMID 22247653, 2011). "It is also possible that a factor in serum affects the stability of TK1 in serum, acting differently in healthy people compared to cancer patients." (PMID 22247653, 2011). "In patients with malignancies more than 95% of the TK1 activity in serum is derived from the malignant cells." (PMID 19396699, 2009). "This study provides a way to explore and repurpose novel inhibitors of TK1 and PKAc and identify new therapeutic targets, which may block glycosylation in cancer treatment." (PMID 40699738, 2025). "Initially, two target proteins, TK1 and the catalytic subunit of cAMP-dependent protein kinase (PKAc), were identified based on their role in different cancer pathways through manual curation, although their direct involvement in glycosylation still requires elucidation." (PMID 40699738, 2025). "Thus, the binding of Tunicamycin C induces a conformational variation that results in structural changes that inhibit TK1 and PKAc, which halts cancer cell proliferation." (PMID 40699738, 2025). "Considering that TK1 was upregulated in most cancers, whether it could predict prognosis was unclear." (PMID 38480789, 2024). "The level of TK1 expression was upregulated in 25 cancers except Kidney Chromophobe (KICH)." (PMID 38480789, 2024). "We demonstrate that the TK1 enzyme activity is higher in EVs derived from the malignant cell lines, with the highest activity from cells deriving from the most aggressive cancer, compared to the prostasomes from healthy individuals and prostate epithelial normal cell line." (PMID 39006942, 2024). "The HPA database shows that TK1 is highly expressed in cancer tissues." (PMID 37767092, 2023). "Furthermore, other rate-limiting enzymes, such as thymidylate synthase (TYMS), thymidine kinase 1 (TK1), and deoxythymidylate kinase (DTYMK), are upregulated in HCC and are associated with poor prognosis and cancer stemness." (PMID 36835122, 2023). "Next, we wanted to investigate if TK1 was influencing cancer-promoting pathways." (PMID 38033034, 2023). "TK1 activity is correlated with cell proliferation and cancer pathogenesis." (PMID 36674619, 2023). "RRM2 and TK1 had remarkably increased expression levels in several cancers." (PMID 37999212, 2023). "Serum TK1 expression up in breast, prostate, lung, esophageal cancers." (PMID 37810966, 2023). "Serum TK1 concentration also indicates the prognostic potential of patients with malignant tumors." (PMID 37767092, 2023). "For example, TK1 serum levels progressively increase with cancer grade (T1-T4) in breast tissue." (PMID 38033034, 2023).
cancer (continued). "We performed correlation studies using RNA-seq data from BRCA patients in TCGA (n = 1093) to test for relationships between TK1 expression and known factors within cancer-promoting pathways including invasion, apoptosis, and cell cycle checkpoint using the online TIMER bioinformatic program." (PMID 38033034, 2023). "Based on results from our RNA-seq study, and because of the direct role of TK1 in DNA synthesis, we aimed to determine whether TK1 levels were promoting cancer via a cell cycle checkpoint pathway." (PMID 38033034, 2023). "Since then, emerging studies have shown that high levels of TK1 expression are a predictive factor in the assessment of early screening, diagnosis, progression, and treatment effects of several cancers, including lung, ovarian, colon, cervix, breast, kidney, prostate, and hematological malignancies." (PMID 36831773, 2023). "In addition, we measured the expression patterns of TK1 from a pan-cancer perspective through the Oncomine and GEPIA2 databases." (PMID 36831773, 2023). "However, in accelerated or uncontrolled proliferation, such as in cancer cells, TK1 remains elevated throughout the S and G2/M phases." (PMID 36201558, 2022). "Once we confirmed the binding of the fragments to purified recombinant TK1 and validated their specificity using a TK1 siRNA knockdown we proceeded to test their capacity to detect TK1 in cell lysates of different cancer cell lines, including, NCI-H460, HT-29, MDA-MB-231, PC3 and human MNC." (PMID 35239730, 2022). "TK1 overexpression may not only be a by-product of cancer cell processes but rather, part of a selective process that aids cancer cell progression." (PMID 36035114, 2022). "This evidence together suggests that the targeting of TK1 both inside the cell and its mTK1 form could be possible approaches for the development of novel cancer therapies." (PMID 35239730, 2022). "Besides, its overexpression in cancer types has indicated that TK1 is a promising biomarker for clinical detection." (PMID 35311151, 2022). "Therefore, imunoassays measuring both active and inactive forms of serum TK1 are most likely superior tools for in-vitro diagnostics of different cancer diseases." (PMID 36201558, 2022). "The molecular mechanisms of intracellular TK1 overexpression have not been established, and its association with cancer progression has not been sufficiently explored." (PMID 36035114, 2022). "In addition, we also discovered the differential expression of PRDM1 and TK1 in Rb subtypes, which are known epigenetic regulators in other cancers." (PMID 35626705, 2022). "However, this approach has not been evaluated in animal models so further studies are required to determine the translational aspect of targeting TK1 with monoclonal antibodies in cancer." (PMID 35203388, 2022). "We found that TK1 was upregulated in most human cancers, including PCa (p < 0.05)." (PMID 35559045, 2022). "Methylation of TK1 may indicate cancer immune infiltration and response to immunotherapeutic agents in patients with PCa." (PMID 36035114, 2022). "Furthermore, the flow cytometry data showed that the nanobodies can potentially be used to target cancer cells expressing TK1, particularly mTK1." (PMID 35239730, 2022). "In addition, TK1 has been applied in cancer screening and chemotherapy monitoring in several clinical practices." (PMID 35311151, 2022). "TK1 is dysregulated in several cancer types and plays a vital role in cancer onset and progression." (PMID 36035114, 2022). "Emerging evidence has shown that TK1 is highly expressed across diverse cancers." (PMID 35311151, 2022). "Previously it has been shown that anti-TK1 monoclonal antibodies could be used for the immunotargeting of TK1 on several cancer types." (PMID 35239730, 2022). "TK1 has long been used as a diagnostic and prognostic marker in AML, and PCMTD2 and LRRC40 have been used as diagnostic or prognostic markers in other types of cancer." (PMID 35656299, 2022).